MIR4276 (microRNA 4276)
Synonyms: hsa-mir-4276
Gene: MicroRNA gene on chromosome 4 (174,423,795 to 174,423,864, forward strand). Ensembl gene ENSG00000265846.
Homologues: Orthologues: chimpanzee MIR4276 (100% identical).